GPR18 (G protein-coupled receptor 18)
Diseases named in the same sentence as GPR18 in open-access papers (continued):
Sharing a sentence is not in itself a finding about the gene and the disease.
cancer (continued). "In addition, GPR18 is closely co-expressed with several cytotoxic CD8+ T-cell markers in 28/29 cancer types, indicating that GPR18-expressing TIL-B-cells may be specifically linked to cytotoxic T-cell functions across human cancers." (PMID 32398659, 2020). "Due to the apparent importance of their receptors in certain cancer types, two atypical cannabinoids, abnormal CBD (Abn-CBD) and O-1602 that mediate their effects through GPR55 and GPR18, were selected in our study." (PMID 31611800, 2019). "For example, overexpression of GRB10 and TDRD9 may enhance cancer cell proliferation, while downregulation of BCL7A, GPR18, KLRG1, and THEM4 could contribute to reduced immune surveillance and tumor evasion." (PMID 39867577, 2024). "The correlation between GPR18 expression and immune cell infiltration in cancer is more complex, showing both positive and negative correlations depending on the cancer type." (PMID 39867577, 2024). "Two other potential receptors that could represent CBRs expressed in cancer cells are GPR55 and GPR18." (PMID 35328467, 2022). "GPR18 should warrant single gene clinical utility assessments over CD20 for patient outcome prediction, as well as further biological investigations across cancers." (PMID 32398659, 2020). "Next, we independently examined the prognosticity of GPR18 mRNA expressions in several non-TCGA cancer cohorts with long-term survival data (>150 months or 12 years) and microarray RNA expression data." (PMID 32398659, 2020). "To further identify the possible immune functions of GPR18 in GPR18-prognostic cancers, we determined immune gene signatures that clustered with GPR18 by non-hierarchical clustering of expression correlations of all 114 TIL-B marker genes defined by TIMER." (PMID 32398659, 2020). "On the other hand, an involvement of FPR1, GPR18 and others in cancer promotion has not been described." (PMID 29861840, 2018). "GPR18’s immune signature denotes apparent B-cell–T-cell interactions (distinct from MS4A1’s “B-cell only” signature), with its intratumoral expressions tied to major cytolytic T-cell functionality scores across 28 cancers, including the cytolytic/IFN-gamma/T-effector (Teff) signature scores." (PMID 32398659, 2020). "Thus, GPR18 levels appear to be prognostic in both TCGA and non-TCGA cancers." (PMID 32398659, 2020). "Similarly, while both Δ9-THC and CP-55,940 act as full agonists at both GPR18 and GPR55, both of these cannabinoid ligands are unable to bind non-canonical CBRs expressed in all the cancer cells investigated." (PMID 35328467, 2022).
tumor (9 papers, 2016 to 2025). "GPR18, with its dual and context-dependent roles, is involved in immune cell recruitment and modulation, reflecting its complex contribution to tumor immune microenvironments." (PMID 39867577, 2024). "RvD2 suppresses tumor growth and enhances clearance of tumor cell debris, while DRV2/GPR18-deficient mice display defective tumor clearance." (PMID 35508275, 2022). "Vascular cells also express CB1 and GPR18, which mediate vasodilation on agonist binding and thereby increase the tumor’s blood supply." (PMID 26875980, 2016). "This context-dependent effect of GPR18 highlights its multifaceted role in modulating immune responses, which may vary depending on the tumor microenvironment." (PMID 39867577, 2024). "The expression levels of the distinct genes of the RvD pathway ALOX15, ALOX15, FPR2, GPR18, GPR32, HPGD and PTGR1 were leveraged from 516 bulk tumor HNSC RNA-seq data, profiled by TCGA and plotted as a heatmap of individual tumor samples." (PMID 35742918, 2022). "However, the precise role of GPR18 in tumor diseases remains unclear." (PMID 33802282, 2021). "Other receptors, such as GPR18 and GPR35, have also been identified as modulators of tumor progression, but the actual effect of cannabinoids on these receptors is still unclear." (PMID 31611800, 2019). "Our studies suggest that small molecule agonists of GPR18 might augment the size of the KLRG1+ effector CD8 T cell compartment, an effect that might be beneficial, for example, during viral responses or in the context of tumor immunotherapy." (PMID 29670628, 2018).
infection (8 papers, 2015 to 2025). The state of being infected such as from the introduction of a foreign agent such as serum, vaccine, antigenic substance or organism. "They bind to the cell surface receptor GPR18/DRV2 providing significant protection in infection-induced inflammation." (PMID 39347277, 2024). "The CeD-dominated cluster C1 differentially expressed genes including TRGC2, IKZF2, GPR18, TRDC and KLHL42 that are associated with ‘infection’ related response pathways including ‘NOD-like receptor signaling pathway’ in gene ontology analysis." (PMID 35995787, 2022). "Resolvins of the D-series are derived from docosahexaenoic acid (DHA) and include RvD2 (7S,16R,17S-trihydroxy-4Z,8E,10Z,12E,14E,19Z-DHA), which binds to the cell surface receptor GPR18/DRV2 providing significant protection in infection-induced inflammation." (PMID 29922275, 2018). "Lastly, GPR18, also known as N-arachidonyl glycine receptor, is ubiquitously expressed in channel catfish (Ictalurus punctatus) tissues, and its immunostimulatory action in response to infection with Aeromonas hydrophila has been proven." (PMID 27610085, 2016). "Transcriptional profiles of the genes CD38, Gpr18, Fpr2 (markers of classically activated macrophages), Arg1, and Egr2 (markers of alternatively activated macrophages) are significantly activated after infection with all viruses." (PMID 38473707, 2024). "Gpr18-/- and control chimeras lost and regained weight after infection with equivalent kinetics." (PMID 26197390, 2015). "Moreover, antibody responses following immunization with hapten-protein conjugates or infection with West Nile virus are normal in Gpr18-/- mice." (PMID 26197390, 2015).
cardiovascular disease (2 papers, 2018 to 2026). "These vascular bed-specific differences highlight the need to consider tissue context in the development of GPR18-based vasculoprotective therapies for cardiovascular disease." (PMID 41596488, 2026). "These vascular bed-specific differences may guide future efforts to develop GPR18-targeted approaches to preserve vascular function in cardiovascular disease." (PMID 41596488, 2026). "Although the mechanism behind vascular bed-specific contractile modulations through GPR18 remains unclear, this may have important implications for the further development of pro-resolution treatments for cardiovascular disease through GPR18 agonism." (PMID 41596488, 2026).
gastrointestinal disorders (1 paper, 2021). "However, the effects of GPR18 antagonists on food intake and body weight were specific and unrelated to visceral illness, stress or changes in the spontaneous activity, while the GPR18 agonist was likely to affect body weight by inducing gastrointestinal disorders, such as nausea." (PMID 33809564, 2021).
lung (1 paper, 2025). "With the rise of cannabinoids as a potential therapeutic agent in several inflammatory disease states, many studies have specifically evaluated their anti-inflammatory effects via CB2 receptors and non-cannabinoid receptors, such as GPR18, in infectious lung injury." (PMID 41282589, 2025).
GPR18 also shares sentences with these, for which no sentence is quoted: metabolic disease (4 papers); metastatic melanoma (3); Anxiety (2); bacterial infections (2); Duchenne muscular dystrophy (2); hepatocellular carcinoma (2); peritonitis (2); abdominal aortic aneurysm (1); arterial diseases (1); Arthritis (1); cerebral infarct (1); Cerebral ischemia (1); chronic hepatitis B infection (1); diabetes (1); gastrointestinal disease (1); inflammation (1); mesothelioma (1); multiple sclerosis (1); oral cancer (1); osteoarthritis (1); periodontal disease (1); placenta disorder (1); skin cutaneous melanoma (1); ulcerative colitis (1).